MYC (MYC proto-oncogene, bHLH transcription factor)
Diseases named in the same sentence as MYC in open-access papers (continued):
Sharing a sentence is not in itself a finding about the gene and the disease.
colon carcinoma (continued). "Using 13C-tryptophan and mass spectrometry, we found that the conversion of tryptophan into kynurenine was greater in MYC-driven colon cancer cells than normal primary colonic epithelial cells." (PMID 31922097, 2020). "MYC also induces the expression of the enzyme arylformamidase (AFMID) in cultured colon cancer cells." (PMID 31922097, 2020). "The c-MYC oncoprotein, a known regulator of glucose metabolism and has previously been linked to EPHB4 in colon carcinoma cells." (PMID 31641103, 2019). "MYC proteins are overexpressed in more than half of all human cancers, including lung, breast, and colon cancers." (PMID 30451365, 2019). "The proto-oncogene MYC is one of the most critical genes activated downstream the WNT pathway in colon cancer." (PMID 31623618, 2019). "We chose RKO cells, a diploid chromosomally stable colon cancer line that has robust mitotic and apoptotic controls which are modulated by MYC." (PMID 31455158, 2019). "MYC is one of the most commonly overexpressed genes in human tumors and is required for maintenance of most cancers, including colon cancer." (PMID 31416966, 2019). "Recently, our laboratory discovered that the proto-oncogene MYC induces AHR expression in colon cancer." (PMID 31416966, 2019). "To validate these results, we performed RT-qPCR for SLC1A5, SLC7A5, TPH1, TDO2, IDO1, AHR, and MYC in colon cancer and normal tissue of the same patients." (PMID 31416966, 2019). "Similar to LEF1, other WNT-related genes found in our RNA-seq to be regulated by MYC such as FOXQ1 and LRP6, were also transcriptionally repressed upon MYC knockdown in colon cancer cells." (PMID 31623618, 2019). "Taken together, our results indicate that Trp transporters and Trp-metabolizing enzymes are up-regulated by MYC in colon cancer cells." (PMID 31416966, 2019). "Our results demonstrate that increased LEF1 expression by MYC led to the retention of β-catenin in the nucleus of normal and colon cancer cells." (PMID 31623618, 2019). "For over two decades MYC has been studied as the most critical pro-proliferative target gene of the WNT pathway in colon cancer." (PMID 31623618, 2019). "We chose to work with the HCT-116 colon carcinoma cells where multiple Wnt-responsive enhancers have been reported to regulate MYC expression." (PMID 29882899, 2018). "YAP1 regulates the expression of SOX2 and c-MYC, which are overexpressed in colon cancer and promote metastasis and tumor growth." (PMID 29416778, 2018). "Commonly mutated genes in colon cancer are APC tumor-suppressor gene, KRAS proto-oncogene, and MYC proto-oncogene." (PMID 29419804, 2018). "This acetyltransferase is overexpressed in hematopoietic malignancies and in several types of carcinoma, e.g., colon cancer, where MYC was found to promote its expression, thus strengthening an inverse relationship between MYC and PGC1α." (PMID 29361779, 2018). "This region is known to contain tissue specific enhancers that drive c-MYC expression in colon cancers." (PMID 29073141, 2017). "CCAT1, located in the vicinity of c-MYC, is abnormally expressed in colon cancer and is dysregulated in many other cancers." (PMID 27566568, 2016). "Consistent with the opposite regulation during the transition phase, NR1H3 have been reported to suppress MYC expression in colon cancer cells." (PMID 25887780, 2015). "In this study, we showed that c-MYC confers resistance to 5-FU by regulating ABCB5 expression in human colon cancer cells." (PMID 25689483, 2015). "Taken together, these results suggest that c-MYC confers resistance to 5-FU through regulating ABCB5 expression in human colon cancer cells." (PMID 25689483, 2015). "For example, CDX2, one caudal-related homeobox transcription factor, mediates E-selectin ligand expression in colon cancer cells with MYC together." (PMID 26083494, 2015).
colon carcinoma (continued). "c-MYC overexpression is frequently observed in various cancers including colon cancer and regulates many biological activities such as aberrant cell proliferation, apoptosis, genomic instability, immortalization and drug resistance." (PMID 25689483, 2015). "Supporting this finding, overexpression of exogenous c-MYC increased the survival rate following 5-FU treatment in human colon cancer cells, and knockdown of endogenous c-MYC decreased it." (PMID 25689483, 2015). "Cancer-related gene c-MYC promoter was validated to combine with CD44 in colon cancer stem cells; SOX2 was chosen for its indispensable position in various CSCs." (PMID 26540347, 2015). "Our data show thattranscriptional activation by MYC in colon cancer cells requires the continuous degradation of MIZ1and identify a novel principle that allows for inhibition of MYC function in tumor cells." (PMID 25253726, 2014). "What We should also noticed is that, by targeting MNT, a MYC antagonist, miR-210 promotes cell cycle progression in transformed cells such as colon cancer cells and cervical cancer cells." (PMID 24586608, 2014). "Collectively, the data establish that these compounds block MYC-dependent transcriptionalactivation via inhibition of HUWE1 in colon cancer cells." (PMID 25253726, 2014). "Here, we used bothshRNAs and small molecule inhibitors to explore the role of HUWE1 as a regulator of MYC function inhuman colon cancer cells." (PMID 25253726, 2014). "A recent study, using homozygous isoform-specific FBW7-null mutations in human colon cancer HCT116 cells, has shown that FBW7α is the major isoform contributing to c-MYC and SREBP degradation." (PMID 23776410, 2013). "Previous reports have shown that both KRAS and β-catenin are able to regulate MYC expression in colon cancer cells." (PMID 23227266, 2012). "DNA hypomethylation also causes activation of genes normally transcriptionally downregulated by hypermethylation of their promoter region (ie, the oncogenes H-ras and c-MYC, which are frequently overexpressed by colon cancer cells)." (PMID 24392268, 2012). "The importance of maintaining appropriate MYC levels for cellular homeostasis is underscored by the finding that the MYC gene is frequently over-expressed in numerous cancers including up to 80% of colon carcinomas." (PMID 21533051, 2011). "The data presented here indicate that a series of chromatin loops are juxtaposed to the MYC promoter at levels equivalent in colon carcinoma and non-colon carcinoma cell lines." (PMID 21533051, 2011). "ß-Catenin/TCF4 complexes were shown to regulate MYC expression in colon cancer cells through two proximal Wnt/ß-catenin responsive enhancers (WREs)." (PMID 21533051, 2011). "We have initiated studies in a mouse model system to begin to decipher the roles of Wnt/ß-catenin and mitogen regulation of MYC expression in normal gastrointestinal physiology and in the pathophysiology of colon cancer." (PMID 21533051, 2011). "Together these data suggest that long-range chromatin loops position distal enhancer elements to the MYC promoter and that this conformation is poised to recruit ß-catenin/TCF4 complexes to regulate MYC expression in colon cancer cells." (PMID 21533051, 2011). "Together, these results suggest that both static and dynamic loops mediate the alignment of the distal MYC enhancers and the MYC promoter in colon cancer cells." (PMID 21533051, 2011). "The elevated MYC levels in colon cancer cells are attributed in part to ß-catenin/TCF4 transcription complexes that are assembled at proximal Wnt/ß-catenin responsive enhancers (WREs)." (PMID 21533051, 2011).
colon carcinoma (continued). "Our previous work implicated a role for ß-catenin/TCF4 complexes in mediating the interaction between the MYC 3′ WRE and the MYC promoter in colon cancer cells." (PMID 21533051, 2011). "The interplay between the precise mechanisms that lead to oncogenic MYC levels in colon cancer cells is yet to be fully understood." (PMID 21533051, 2011). "Notably, previous studies have shown that ID1, ID3, and c-MYC help maintain the self-renewal capacity of colon cancer stem cells." (PMID 40399276, 2025). "The expression levels of the MYC protein in SW620-nkd1−/− cells treated with CHX and CQ were notably greater than those in the cells treated with only CHX, indicating that NKD1 gene knockout considerably increases MYC protein autophagic degradation in colon cancer cells." (PMID 40675969, 2025). "Moreover, the expression levels of NKD1 and MYC in normal colon tissues and colon cancer tissues were determined via immunohistochemistry (IHC)." (PMID 40675969, 2025). "This regulation was also found in representative upregulated genes for CMS2, including the WNT pathway target gene LGR5, which is an important marker of colon cancer stem cells, and the oncogenic transcription factor MYC, which regulates tumour growth, differentiation, and proliferation." (PMID 38339195, 2024). "Similarly, the same association as CBLL1 was found for the LGR5 gene, a cancer stem cell biomarker in colon cancer, as well as with the transcription factor c-MYC, which is a well-known universal marker of CSCs." (PMID 38339195, 2024). "In summary, we found that shikonin suppresses colon cancer cell proliferation and migration through cellular experiments and identified eight genes (CCNB3, IL-1α, CXCL8, CDKN2A, MYC, IGFBP3, SQSTM1, and GADD45G) associated with cell senescence through systematic bioinformatics analysis." (PMID 39188951, 2024). "JUN is overregulated in three of the five datasets and is related to: 1) colon cancer signaling pathways along with MYC; 2) the focal adhesion pathway along with ELK1; 3) pathways in cancer along with ELK1 and MYC; 4) EBV infection along with MYC; and 5) angiogenesis." (PMID 39228892, 2024). "Moreover, studies on human colon cancer cells have shown that MYC activates the expression of LEF1, thus promoting cell proliferation, and that LEF1 also plays a pivotal role in regulating lineage differentiation in pluripotent stem cells." (PMID 38474345, 2024). "We then hypothesized that C.B CM can improve the 5-FU chemo sensitivity in colon cancer cells by downregulating TYMS through the inhibition of MYC." (PMID 36941257, 2023). "MIR34A expression resulted in downregulation of the stemness factors BMI1 proto-oncogene polycomb ring finger (BMI1), CD44, CD133, olfactomedin 4 (OLFM4), and MYC proto-oncogene bHLH transcription factor (MYC) in a colon cancer cell line, clearly connecting this axis to stemness." (PMID 38009093, 2023). "In addition, they found that simultaneous inhibition of ODC and eIF5A can downregulate MYC expression and decrease colon cancer cell growth." (PMID 37895010, 2023). "Beyond the embryonic transcription factors OCT4, NANOG, and putative miR-1305 interference, POLR3G expression is also regulated by MYC and sensitive to MYC disruption in cancers featuring MYC upregulation, including colon carcinoma and acute myeloid leukemia cell lines." (PMID 36710885, 2022). "They showed that this treatment strategy caused cell cycle arrest at the G1 phase in female (HT-29) and male (SW480) colon cancer cells by decreasing the expression of MYC, MYB, and the PROX1 oncogenes and increasing the expression of the p21Waf1/Cip1 and p27Kip1 cell cycle inhibitors." (PMID 36412903, 2022). "Importantly, the facilitated nuclear export rate of MYC mRNAs was the sole parameter responsible for the increased MYC expression in colon cancer cells (HCT-116) compared to primary human colon epithelial cells." (PMID 35017527, 2022).
colon carcinoma (continued). "A recent study showed that the amplification of MYC in colon cancer is triggered by ecDNA hubs." (PMID 36184613, 2022). "Thus, FOXQ1-mediated activation of c-MYC signaling and polyamine synthesis is an intrinsic molecular phenotype of colon cancer." (PMID 36457036, 2022). "Whether miR-26a could mediate MYC inhibition to complete the full MYC/miR-26a regulatory loop in colon cancer needs to be further studied." (PMID 35120580, 2022). "Cordycepin could be considered as a treatment option for colon cancer by regulating the MYC/miR-26a pathway." (PMID 35120580, 2022). "The expression of CCAT1, an lncRNA transcribed from a distinct c-MYC SE in CIMP + colon cancers, predicted JQ1 sensitivity and BET-mediated c-MYC transcription, suggesting it as a clinically tractable biomarker for identifying patients who will likely benefit from BET inhibitors." (PMID 35277481, 2022). "Of special interest might be our recent observation of MYC, as a potential regulator of survival in colon carcinoma-specific CSCs." (PMID 33800955, 2021). "Hence, this research was designed to explore the mechanism underlying the OLR1/c-MYC/SULT2B1 axis in the regulation of glycolytic metabolism, to affect colon cancer cell proliferation and chemoresistance." (PMID 34921134, 2021). "The results suggested that knockdown of c-MYC could inhibit glycolytic metabolism of colon cancer cells." (PMID 34921134, 2021). "The results showed that OLR1 expression was positively correlated with c-MYC in colon cancer, indicting OLR1 might promote c-MYC expression in colon cancer." (PMID 34921134, 2021). "In order to further explore whether c-MYC manipulated glycolytic metabolism through SULT2B1 to affect the proliferation and chemoresistance of colon cancer cells, we successfully constructed a cell line with c-MYC knockdown and SULT2B1 overexpression." (PMID 34921134, 2021). "CCAT2 partakes in the development of colon cancer by regulating MYC and Wnt." (PMID 34499007, 2021). "Generally speaking, knockdown of OLR1 might inhibit the tumorigenicity and chemoresistance of colon cancer cells in nude mice by downregulating c-MYC and SULT2B1." (PMID 34921134, 2021). "Collectively, knockdown of OLR1 could inhibit the proliferation and chemoresistance of colon cancer cells via c-MYC downregulation." (PMID 34921134, 2021). "Enhanced expression of CMPK2 lncRNA, which stabilizes far upstream element (FUSE)-binding protein 3 (FUBP3) and promotes its binding to the MYC gene regulatory element, was also found in colon cancer cells, resulting in activation of transcription of the MYC proto-oncogene." (PMID 34440124, 2021). "Notably, one of the most highly downregulated genes in CIMP+ cells upon JQ1 treatment was the CCAT1 transcript, a lncRNA expressed in colon cancers and reported to regulate MYC expression." (PMID 34065438, 2021). "Conclusively, knockdown of OLR1 might diminish SULT2B1 expression by downregulating c-MYC, thereby restraining glycolytic metabolism to inhibit colon cancer cell proliferation and chemoresistance." (PMID 34921134, 2021). "However, the mechanism of c-MYC in glycolytic metabolism and chemoresistance in colon cancer remained to be further investigated." (PMID 34921134, 2021). "Taken together, SULT2B1 was highly expressed in colon cancer cells, and knockdown of c-MYC could disturb SULT2B1 expression and inhibit the glycolytic metabolism of colon cancer cells." (PMID 34921134, 2021). "Mechanistically, OLR1 increased c-MYC expression to upregulate SULT2B1 in colon cancer cells." (PMID 34921134, 2021). "Similarly, CASC21 is located in the 8q24 locus and we observed a positive relationship between CASC21 and MYC expression, providing the evidence for its potential oncogenic role in colon cancer." (PMID 31965704, 2020). "Infection with P. gingivalis could activate JAK/STAT3 pathway in normal gingival epithelial cells, While F. nucleatum could upregulate MYC in colon cancer cells through E-cadherin pathway." (PMID 33391626, 2020).
colon carcinoma (continued). "Moreover, MYC up-regulation increases the synthesis of rRNA and the rate of protein translation in colon cancer cells, thus counteracting the ribosomal stress induced by Dox." (PMID 32599901, 2020). "Furthermore, in colon cancer, the internalized CD44 and acetyltransferase p300 induce STAT3 acetylation at Lysine (Lys) 685, which in turn promotes the expression of cell cycle regulators cyclin D1 70, MYC, and Twist1 in colon cancer cells." (PMID 32754274, 2020). "The underlying mechanisms of MYC dysregulation contributing to colon cancer progression are still not fully resolved." (PMID 33170148, 2020). "However, mRNA level of STAT3 was reported consistent with protein level in gingival epithelial cells and MYC mRNA and protein level was found closely related in colon cancer cells after Fusobacterial infection." (PMID 33391626, 2020). "It was shown that stimulation of PPAR-γ in cancers affects the expression of several genes associated with apoptosis, i.e. MYC in thyroid cancer, GADD153 (growth arrest and DNA damage-inducible 153) in colon cancer and LC and POX (proline oxidase) in colon cancer." (PMID 31993929, 2020). "To determine whether MYC is responsible for increased Trp and Kyn in colon cancer cells, we expressed MYC in HCECs and quantified Trp and Kyn by LC-MS/MS and found that MYC expression caused an increase in Trp and Kyn in HCECs." (PMID 31416966, 2019). "Hence, our results suggest that MYC-dependent colon cancer cell are specifically sensitive to reduction in LEF1 expression." (PMID 31623618, 2019). "To determine whether MYC regulated the expression of Trp-related genes in established colon cancer cells, we knocked down MYC in DLD1 cells." (PMID 31416966, 2019). "Activation of the WNT pathway drives colon cancer in mice in a MYC-dependent manner." (PMID 31416966, 2019). "MYC activates the transcription of LEF1 and is required for LEF1 expression in colon cancer cells and in primary colonic cells transformed by APC loss of function, a common mutation in colon cancer patients." (PMID 31623618, 2019). "Knocking down MYC reduced LEF1 protein in colon cancer cells such as RKO and DLD1." (PMID 31623618, 2019). "This led us to test in colon carcinoma cells if distal MYC enhancers that are responsive to Wnt signaling could differentially regulate the endogenous activity of the two promoters." (PMID 29882899, 2018). "A network-based analysis of colon cancer splicing changes reported noteworthy differences in the induction of various transcription factors such as MYC and ELK1, and supported our findings with respect to the activation of signaling pathways upon PRPF overexpression." (PMID 28915620, 2017). "In this study, we observed that PRPF overexpression decreased the intracellular levels of reactive oxygen species, and inhibited resveratrol-induced apoptosis by activating the cell survival signaling proteins NFκB, ERK, and c-MYC in HCT116 human colon cancer cells." (PMID 28915620, 2017). "Furthermore, the fact that LTC4 signaling also reduced the expression of c-MYC is an interesting observation consistent with the proposed anti-tumor effect of LTC4 in colon cancer cells." (PMID 28402256, 2017). "Besides, an heterogeneous pattern of ARNTL, WEE and c-MYC expression hallmarked the chosen colon cancer cell lines and likely influenced their phenotypic changes." (PMID 26768731, 2016). "Given that ABC transporters contribute to the resistance to chemotherapeutic agents by causing the efflux of anti-cancer drugs, we have been suggested that c-MYC increases 5-FU resistance in human colon cancer cells by regulating the expression of ABC transporters." (PMID 25689483, 2015). "To identify the ABC transporter genes regulated by c-MYC in human colon cancer cells, we investigated the effect of c-MYC knockdown on MDR1, MRP1, ABCB5, ABCC4 and ABCC5 expression levels, which are closely involved in the resistance to chemotherapeutic agents including 5-FU 17–23." (PMID 25689483, 2015).